CTNNB1 (catenin beta 1)
Diseases named in the same sentence as CTNNB1 in open-access papers (continued):
Sharing a sentence is not in itself a finding about the gene and the disease.
colon carcinoma (continued). "To validate whether a correlation of EpCAM and BCL9/CTNNB1 exists in cancers, we analyzed the correlations of EpCAM and BCL9 as well as EpCAM and CTNNB1 in lung cancer, colon cancer, esophageal cancer, stomach cancer, head and neck cancer, and kidney cancer." (PMID 34790117, 2021). "We conclude that in colon cancers, the Ser45 mutation does not appear to increase Wnt signaling and that the effects of CTNNB1 mutations are not the same in the liver and colon." (PMID 32751567, 2020). "Furthermore, we demonstrated that p22 can increase TCF/β-catenin transcription on its own and in conjunction with ectopically expressed wild-type or mutant β-catenin; and in colon cancer cells with endogenous mutant APC (SW480 cells) or CTNNB1 (HCT116 cells)." (PMID 32486480, 2020). "However, in colon cancer patients, β-catenin (CTNNB1) and TGFBR2 were all unfavorable effects on tumor progress." (PMID 31221124, 2019). "In addition, another gene CTNNB1 reported to affect colon cancer progression was also involved in this miRNA-gene network in stage II." (PMID 31888617, 2019). "Interestingly, we found that ACLY was positively related to CTNNB1 in colon cancer tissues (r = 0.5871, P < 0.001)." (PMID 31511060, 2019). "Moreover, we found that knockdown of CTNNB1 weakened the effects of ACLY on colon cancer cell migration and invasion." (PMID 31511060, 2019). "Some CTNNB1 target genes were differently regulated by ACLY in different colon cancer cells." (PMID 31511060, 2019). "We also found Sox9 overexpression in chemically induced colon tumors and in Apc and Ctnnb1 mutants." (PMID 27811361, 2016). "The strong inhibitory effect on the active pool of β-catenin compared to that for total β-catenin when CTNNB1 transcript levels were reduced in HCECs was further studied in three human colon cancer cell lines stably transduced with the two DOX-inducible CTNNB1 shRNAs." (PMID 26528816, 2015). "Synergistic interactions between trametinib and ICG-001 were investigated in a panel of cell lines, including three CTNNB1-wild type colon cancer cell lines, three CTNNB1-mutant colon cancer cell lines, and a pair of CTNNB1-mutant and CTNNB1-wild type lung cancer cell lines." (PMID 26018524, 2015). "We used two different doxycycline-induced shRNAs against CTNNB1 to study effects of antagonizing CTNNB1 endogenous transcript levels in the DLD1 human colon cancer cell line, which harbor APC defects leading to constitutive activation of β-catenin/TCF signaling." (PMID 26528816, 2015). "Transcriptional profiling was used to identify Wnt/CTNNB1 target genes in colon cancer cells." (PMID 24651522, 2014). "For example, mutations in the β-catenin/CTNNB1 gene have been reported in aggressive fibromatosis (also called desmoid tumor) and parathyroid tumors and mutations in the APC gene are often found in colon cancers." (PMID 20459685, 2010). "Moreover, the nuclear accumulation of CTNNB1, a key member of WNT/CTNNB1 pathway, might indicate higher rate of metastasis in colon cancer." (PMID 31511060, 2019). "The complex may increase the stability of CTNNB1 protein and facilitate the accumulation of CTNNB1 in the nucleus, subsequently promoting the CTNNB1 transcriptional activity and the migration and invasion abilities of colon cancer." (PMID 31511060, 2019). "ACLY could stabilize CTNNB1 (beta-catenin 1) protein by interacting, and the complex might promote CTNNB1 translocation through cytoplasm to nucleus, subsequently promote the CTNNB1 transcriptional activity and migration and invasion abilities of colon cancer cells." (PMID 31511060, 2019). "Therefore, we detect the protein levels of ACLY and CTNNB1 in colon cancer pathological tissue." (PMID 31511060, 2019).
colon carcinoma (continued). "The mechanism by which ADT-094 treatment suppresses the oncogenic activity of β-catenin may be at the transcriptional level given that β-catenin mRNA levels and CTNNB1 promoter activity were reduced in colon tumor cells following knockdown of PDE5 or PDE10 or by SS treatment." (PMID 26299804, 2015). "Here we report an integrative analysis of genome-wide chromatin occupancy of CTNNB1 by chromatin immunoprecipitation coupled with high-throughput sequencing (ChIP-seq) and gene expression profiling by microarray analysis upon RNAi-mediated knockdown of CTNNB1 in colon cancer cells." (PMID 24651522, 2014). "qPCR analysis also showed the downregulation of KLF4 and CTNNB1 upon synergistic activity of ZEB and VPA treated colon cancer cells." (PMID 42224286, 2026). "Strikingly, most of the Wnt genes upregulated by HMGA1 in our murine model are also upregulated in human colon cancer, including the WNT effectors, ASCL2, AXIN2, CTNNB1, MYC, EPHB2, CD44, and ETS2 and the WNT receptors, LGR5, LRP5, and LRP6." (PMID 39895630, 2025). "The stabilization of CTNNB1 by ACLY is also indicated to promote cell migration and invasiveness in colon cancer." (PMID 38166604, 2024). "For further analysis, we identified increased expression levels of VEGF-A, CTNNB1, CD44, and MMP7 oncogenic signatures in different colon cancer cell lines." (PMID 36672201, 2023). "This analysis revealed that higher expression levels of CTNNB1 and SOX9 were correlated with low numbers of γδ T cells in human colon cancer." (PMID 37309673, 2023). "When NCKAP1 expression was decreased by siRNA transfection in colon cancer cells, the levels of CDH1 and CTNNB1, which are known as epithelial marker among EMT markers, were increased." (PMID 36639705, 2023). "Further, we identified an imperfect but linear relationship between CHRM1 and APC and CTNNB1 mRNA levels, supporting a relationship between CHRM1/M1R and β-catenin signaling in colon cancer." (PMID 35370785, 2022). "We filtered four genes (BDNF, PTGS2, CTNNB1, and GSK3B) from the colon tumor and matched normal RNA-seq data, estimated the differences in fold change, and performed a t-test to determine the p value representing significant differences." (PMID 35054980, 2022). "Niclosamide, an approved antihelminthic drug for the treatment of tapeworm infections, inhibited metastasis formation in a mouse model of colon cancer by blocking S100A4 expression and its effects on the WNT/CTNNB1 signaling pathway." (PMID 34078355, 2021). "Our findings are in line with previous studies showing that CTNNB1 and JAK family members are colon cancer recurrence-specific genes and prognostic biomarkers." (PMID 32107391, 2020). "Immunohistochemical analysis of 78 colon cancer patients showed that the high expression levels of ACLY and CTNNB1 protein was positively correlated with metastasis of colon cancer." (PMID 31511060, 2019). "After siRNA silencing of APC, β-catenin/CTNNB1 and Evi/Wls, changes in the transcriptome of HCT116 colon cancer cells were analyzed by RNA sequencing (RNAseq)." (PMID 29453334, 2018). "In the present study, we have analyzed the in vivo role of Pygo2 using chemically induced colon cancer and conditional Apc LOF and Ctnnb1 GOF mouse models." (PMID 27811361, 2016). "Two colon cancer cell lines HCT-116 and DLD-1 used in our study have different genetic profile of APC and CTNNB1 genes that could lead to a different Wnt signaling response." (PMID 32784494, 2020). "Among the deregulated genes involved in the EMT signaling, CTNNB1, as well as JAK1 play key roles in colon cancer progression: CTNNB1 through the activation of Wnt/β-catenin signaling, and JAK/STAT pathway by regulating cell survival and proliferation, differentiation and migration." (PMID 32107391, 2020).
colon carcinoma (continued). "Furthermore, we identified that ACLY stabilized CTNNB1 protein by interacting, and the complex might promote CTNNB1 translocation through cytoplasm to nucleus, which promoted the CTNNB1 transcriptional activity and migration and invasion abilities of colon cancer cells." (PMID 31511060, 2019). "As ACLY could stabilize and interact with CTNNB1, and assisted CTNNB1 translocation through cytoplasm to nucleus, ACLY may promote the CTNNB1 transcriptional activity and the migration and invasion abilities of colon cancer cells." (PMID 31511060, 2019). "(H) qRT-PCR for Axin2, Ccnd1, Myc, and Ctnnb1 in HCT116 colon cancer cells treated with miR-31 inhibitor and negative control (NC, Scramble RNA), as well as miR-31 mimics and negative control (NC, Scramble RNA) for 24 hrs." (PMID 28870287, 2017). "In the CTNNB1-wild type colon cancer cell line HCT 15 synergy is observed, and not in other lines such as HCT 116 (mutant), LoVo (wild type) and LS174T (mutant)." (PMID 26018524, 2015). "Our aim was to compare the effects of Tcf-4 knockdown and β-catenin knockdown on cell proliferation, apoptosis, and chemosensitivity in the SW480 (mutant APC, wild-type CTNNB1) and HCT116 (mutant CTNNB1, wild-type APC) colon cancer cell lines using short hairpin RNA (shRNA)." (PMID 23029137, 2012). "However, there is no published research on the relationship between ACLY and CTNNB1 in colon cancer." (PMID 31511060, 2019). "Subsequent combination studies revealed synergic interaction between trametinib and ICG-001 in the CTNNB1-wild type SW620 colon cancer cell line and not in the CTNNB1-mutant colon cancer line SW48." (PMID 26018524, 2015). "Transcriptome analysis of 57 advanced colon cancer samples revealed that one of the non-T cell inflamed subtypes (group 4) had low expression of CD8a, IFNG and GZMB with high expression of SCD1 and CTNNB1(β-catenin) and its downstream molecules including VEGFA and TCF12." (PMID 35793868, 2022). "Interestingly, and in contrast to our expectations, trametinib and ICG-001 appear to work synergistically in the CTNNB1-wild type colon cancer cell line SW620, and not in the CTNNB1-mutant cell line." (PMID 26018524, 2015). "Similarly to APC mutant colon tumours, we do not observe nuclear β-catenin throughout the CU-PC01 tumours, indicating that the additional deregulation of the Wnt pathway from the tumour microenvironment is also involved in activating the pathway even in CTNNB1 mutant cells." (PMID 38667288, 2024).
endometrial cancer (91 papers, 2010 to 2026). Primary or metastatic malignant neoplasm involving the endometrium (mucous membrane that lines the endometrial cavity). "Approximately 30% of patients with endometrial carcinomas (ECs) with exon 3 CTNNB1 (β-catenin) mutations experience disease recurrence, whereas others with the same mutations remain recurrence-free." (PMID 41574604, 2026). "Given the role of CTNNB1 mutations in activating the Wnt/β-catenin signaling pathway, targeting this pathway has emerged as a potential therapeutic strategy for endometrial cancers with CTNNB1 mutations." (PMID 40072110, 2025). "For example, in endometrial cancers, mutations in CTNNB1 frequently co-occur with mutations in PIK3CA, PTEN, and ARID1A, particularly in high-grade endometrioid carcinomas." (PMID 40072110, 2025). "In high-grade endometrial cancers, loss of cell adhesion and activation of oncogenic signaling pathways driven by CTNNB1 mutations contribute to rapid disease progression and metastasis." (PMID 40072110, 2025). "Mutations in PIK3CA, which encodes a subunit of the PI3K enzyme, are also frequently found alongside CTNNB1 mutations in endometrial cancer." (PMID 40072110, 2025). "Although the prognostic impact of CTNNB1 mutations in low-grade early-stage endometrial carcinoma has already been described, the biological mechanisms underlying the aggressive behavior of these tumors remain incompletely understood." (PMID 41227323, 2025). "Overall, these findings support the notion that CTNNB1 mutated endometrial carcinomas adopt a more aggressive phenotype due to enhanced immune evasion mechanisms." (PMID 41227323, 2025). "In this study, we investigate the proteome of low-grade early-stage endometrial carcinomas to explore the biologic impact of CTNNB1 mutations." (PMID 41227323, 2025). "Aggressive behavior observed in CTNNB1 mutated endometrial carcinomas can be explained by their capacity of downregulating the immune system, the potential activation of WNT signaling through non-canonical pathways, and increased cell plasticity." (PMID 41227323, 2025). "In the present work, we aim to harness the power of shotgun proteomics to further explore the biological impact of CTNNB1 mutations using FFPE samples from low-grade early-stage endometrial carcinomas." (PMID 41227323, 2025). "To further investigate these findings, we analyzed the ROR2 expression in a large cohort of low-grade early-stage endometrial carcinomas (150 samples from CTNNB1 wild-type tumors and 15 from mutated counterparts)." (PMID 41227323, 2025). "CTNNB1 mutations, particularly those located in exon 3 of the CTNNB1 gene encoding β-catenin, have emerged as significant factors influencing the clinicopathologic features and prognostic outcomes in endometrial carcinoma." (PMID 40004914, 2025). "Shotgun proteomics reveal that low-grade early-stage endometrial carcinomas with CTNNB1 mutations show dysregulated pathways associated with keratinization, immune dysregulation, and altered calcium homeostasis." (PMID 41227323, 2025). "In this study, we performed shotgun proteomics using Formalin-Fixed Paraffin-Embedded (FFPE) tissue samples of CTNNB1 mutated and wild-type low-risk endometrial carcinomas." (PMID 41227323, 2025). "Studies on endometrial cancer have shown that CTNNB1 mutations are more frequent in Asian individuals compared to black and white individuals." (PMID 39541191, 2024). "Second, proteins such as MMR, L1CAM, and CTNNB1 have recently been reported to be associated with the prognosis of endometrial cancer, and the molecular classification of endometrial cancer proposed by TCGA has also gained wide attention." (PMID 39834947, 2024). "CTNNB1 is one of the most frequently mutated genes in endometrial carcinoma, and mutations occur at an unusually high frequency (~50%) in microsatellite stable, copy number low, and endometrioid carcinomas." (PMID 38539494, 2024).
endometrial cancer (continued). "CTNNB1 point mutations are early events in endometrial carcinoma development, making β-catenin (along with PAX2 and PTEN) a plausible biomarker for endometrioid precancers." (PMID 38539494, 2024). "Previous reports that have evaluated the diagnostic accuracy of β-catenin IHC findings in predicting a CTNNB1 mutation in endometrial cancer showed a high sensitivity and specificity." (PMID 37347751, 2023). "In our study predicted mutations in CTNNB1 were found two types of OC tissues (a case with simultaneous ovarian and endometrial cancers and a clear-cell OC case)." (PMID 36982928, 2023). "This notion is exemplified by the development of endometrial cancer in two woman (subject #39 and #168) with CTNNB1 mutation(s) in our follow-up survey." (PMID 39516270, 2023). "In contrast, we did not observe any association with recurrence in relation to protein expression levels of the other markers, also including B-catenin, although mutations in the CTNNB1 gene have been linked to low-stage recurrence in endometrial cancer." (PMID 37146405, 2023). "In support of this, a prior study has correlated CTNNB1 mutation and β-catenin IHC patterns in endometrial cancer and found that these mutations were present in only 15% of the cases with cytoplasmic β-catenin staining." (PMID 37347751, 2023). "We analyzed the differential expression of miRNAs in 119 endometrial carcinomas, measuring their expression in histological subtypes, molecular subtypes, and tumors with CTNNB1 mutations." (PMID 37958433, 2023). "In this paper, we analyzed the expression of microRNAs in endometrial carcinomas, measuring their expression in histological subtypes, molecular subtypes, and tumors with CTNNB1 mutations." (PMID 37958433, 2023). "Integrated analysis revealed that CTNNB1 exon 3 mutations are associated with an aggressive subtype of low-grade and low-stage endometrial carcinoma in younger women." (PMID 37655825, 2023). "One of such are mutations in the β-catenin (CTNNB1) gene, a frequently mutated gene in endometrial cancer." (PMID 35531470, 2022). "Targeting β-catenin directly in cancer has proved challenging, despite the prognostic value of exon 3 CTNNB1 mutations in endometrial cancer." (PMID 36248967, 2022). "Mutations in CTNNB1 occur early in endometrial cancer pathogenesis, as evidenced by β-catenin dysregulation in atypical hyperplasia." (PMID 36248967, 2022). "It has also been associated with endometrial hyperplasia and endometrial cancer; in low-grade endometrial cancer, CTNNB1 mutations are associated with recurrence-free survival." (PMID 35409214, 2022). "We searched for pathogenic mutation of CTNNB1, a predictor of poor prognostic in endometrial cancer." (PMID 35565317, 2022). "Kim and Jeong summarized activating mutations of CTNNB1 in endometrial cancer cell lines, occurring at some beforementioned and other sites: D32V, S37P, S37C, D207G, and X561_splice." (PMID 35531470, 2022). "A large sequencing study of cancer patients revealed CTNNB1 mutations were most commonly observed in endometrial, liver, and colorectal tumor types, with endometrial cancer being the most prevalent." (PMID 36248967, 2022). "In endometrial cancer, patients with CTNNB1 mutations typically have missense mutations at phosphorylation sites and/or adjacent residues." (PMID 36248967, 2022). "In this study, the CTNNB1 mutation was the significant biomarker of recurrence in low grade, early stage endometrial cancer (HR 4.69)." (PMID 34298845, 2021). "A similar result was also provided in endometrial cancer in an NGS study in which 53 of 245 patients had the CTNNB1 mutation." (PMID 34298845, 2021).